CRAMP1 (cramped chromatin regulator 1)
Description:
Transcription factor, which specifically drives expression of histone H1 genes. Binds to the promoters of H1 genes (H1-2, H1-3, H1-4, H1-5 and H1-10/H1x) together with NPAT and GON4L, positively regulating their transcription.
Synonyms: CRAMP1L; HN1L; KIAA1426; TCE4
Tractability: PROTAC: ubiquitination databases record sites on it.
Gene: Protein-coding gene on chromosome 16 (1,612,337 to 1,677,908, forward strand). Ensembl gene ENSG00000007545.
Subcellular location: Nucleus; Chromosome
Subcellular location (Human Protein Atlas): Nucleoplasm; Cytosol; Nucleoli
Gene Ontology:
Molecular function: DNA-binding transcription factor activity; chromatin binding
Biological process: positive regulation of DNA-templated transcription; pattern specification process
Cellular component: chromosome; histone locus body; nucleus
Genetic constraint (gnomAD): Loss-of-function variants: 45 observed, 84.83 expected, observed/expected ratio (o/e) 0.53, 90% interval 0.42 to 0.68. The synonymous counts are far from expectation, so gnomAD's model fits this gene poorly and the ratio says little. Missense variants: 1,565 observed, 1,486.6 expected, observed/expected ratio (o/e) 1.05, 90% interval 1.01 to 1.1. Synonymous variants: 813 observed, 653.11 expected, observed/expected ratio (o/e) 1.24, 90% interval 1.17 to 1.32.
Homologues: Orthologues: chimpanzee CRAMP1 (99% identical), macaque CRAMP1 (98% identical), guinea pig CRAMP1 (86% identical), mouse Cramp1 (84% identical), rat Cramp1 (84% identical), pig CRAMP1 (82% identical), rabbit CRAMP1 (79% identical), dog CRAMP1 (78% identical), tropical clawed frog cramp1 (59% identical), zebrafish cramp1 (43% identical), Drosophila melanogaster crm (20% identical), Caenorhabditis elegans R151.8 (12% identical).
Diseases named in the same sentence as CRAMP1 in open-access papers:
CRAMP1 is named in the same sentence as 2 diseases in open-access papers, as found by Europe PMC text mining. Sharing a sentence is not in itself a finding about the gene and the disease. The quoted sentences say what the papers report.
infection (1 paper, 2018). The state of being infected such as from the introduction of a foreign agent such as serum, vaccine, antigenic substance or organism. "Since only two transcripts (SFSWAP and CRAMP1) were found downregulated at 6-weeks post-infection, GO analysis did not result in any term overrepresented." (PMID 29615760, 2018).
CRAMP1 also shares sentences with these, for which no sentence is quoted: tumor (1 paper).